HEY1 (hes related family bHLH transcription factor with YRPW motif 1)
Diseases named in the same sentence as HEY1 in open-access papers (continued):
Sharing a sentence is not in itself a finding about the gene and the disease.
male infertility (1 paper, 2023). The inability of the male to effect fertilization of an ovum after a specified period of unprotected intercourse. "Among them, miRNAs (has-miR-3127-5p and has-miR-3184-5p), lncRNAs (AL356488.2 and AL645608.3) and TFs (NANOG and HEY1) as the key regulatory factors of PRM2, FSCN3 and TEKT2, were predicted significantly associated with male infertility." (PMID 37891374, 2023).
malignant myoepithelioma (1 paper, 2022). An infiltrating malignant tumor characterized by the presence of atypical cells with myoepithelial differentiation. "MYC gene amplification was detected in one responder patient affected by malignant myoepithelioma, and MYC amplification associated with HEY1 amplification (possibly due to close chromosomal location) was identified in patient TOMAS-34 (non-responder patient affected by uterine LMS)." (PMID 36110934, 2022).
MELAS (1 paper, 2020). "However, by day 35, mRNA expressions of Notch receptor NOTCH1, NOTCH receptor ligands DLL1 and JAG1 as well as the downstream targets HEY1 and HES5 were significantly higher in day 35 MELAS compared to controls." (PMID 32170107, 2020).
mucinous tumors (1 paper, 2021). "In contrast to non‐mucinous tumors, the mucinous tumors from KLN mice displayed significant up‐regulation of Notch pathway components including Hes1, Hes5, Hey1 and Hey2, but not Wnt nor Hedgehog signaling." (PMID 33439550, 2021).
myocardial ischemia (1 paper, 2021). A disorder of cardiac function caused by insufficient blood flow to the muscle tissue of the heart. "Subanalysis correlating gene expression with proximal RCA occlusion strengthened the discovery of HEY1—a transcriptional suppressor and an atrial NOTCH, TGFbeta, and HIF1 pathway target gene—as an indicator of cardiovascular functional reserve in myocardial ischemia." (PMID 34926599, 2021).
neck tumor (1 paper, 2014). "RT-PCR and Sanger sequencing showed that exon 4 of HEY1 was fused to exon 13 of NCOA2 in the sample from the thigh lesion; we did not have spare material to perform a similar analysis of the neck tumor." (PMID 24839999, 2014).
nephritis (1 paper, 2022). Inflammation of renal tissue. "In murine NTS-nephritis investigated here, Hes-1 and Hey-1 mRNAs were overexpressed at 10 days." (PMID 35215234, 2022).
non-small cell lung carcinoma (1 paper, 2024). A group of at least three distinct histological types of lung cancer, including non-small cell squamous cell carcinoma, adenocarcinoma, and large cell carcinoma. "HEY1 could regulate the cisplatin sensitivity of non-small-cell lung cancer (NSCLC) cells." (PMID 39351154, 2024).
opisthorchiasis (1 paper, 2022). Infection with flukes of the genus Opisthorchis. "For the first time, using histological methods and real-time PCR analysis, we demonstrated the activation of the Jagged1/Notch pathway in liver fibrogenesis, including the activation of the Hes1 and Hey1 target genes during experimental opisthorchiasis in Mesocricetus auratus." (PMID 36355906, 2022).
osteoarthritis (1 paper, 2022). A noninflammatory degenerative joint disease occurring chiefly in older persons, characterized by degeneration of the articular cartilage, hypertrophy of bone at the margins and changes in the synovial membrane. "Hey1 has also been found to be upregulated in osteoarthritis (OA) joint cartilage." (PMID 36377467, 2022).
Osteopenia (1 paper, 2024). Osteopenia is a term to define bone density that is not normal but also not as low as osteoporosis. "Hey1 deficiency led to moderate osteopenia and an increase in the number and activity of osteoclasts cultured ex vivo." (PMID 39595568, 2024). "Overexpression of Hey1 led to distinctly progressive osteopenia and inhibition of osteoblast functions ex vivo." (PMID 39595568, 2024).
pediatric cancer (1 paper, 2023). "When HEY1::NCOA2 was knocked down using human HEY1-specific shRNA sequences, genetic pathways associated with pediatric cancer and proteoglycan synthesis were affected." (PMID 37212282, 2023).
prolactinomas (1 paper, 2017). "Additionally, we show that Notch target gene Hes1 and Hey2 levels were decreased in prolactinoma cell lines, in line with a previous finding in human prolactinomas, while on the contrary, Hey1 was overexpressed in GH3 cells." (PMID 28915655, 2017).
prostate adenocarcinoma (1 paper, 2014). "To know the relative contributions of PTOV1 and Notch signaling to malignancy in PC, we analyzed the expression of PTOV1, HEY1 and HES1 in 45 prostate adenocarcinomas and control associated benign peripheral zone (BPZ) by real-time RT-PCR." (PMID 24684754, 2014).
pulmonary diseases (1 paper, 2019). "A number of these genes have reported associations with COPD or other pulmonary diseases and include; CYP2E1, HEY1, SMAD3, BARD1 and FOXP1." (PMID 31860681, 2019).
renal carcinoma (1 paper, 2019). A carcinoma arising from the epithelium of the renal parenchyma or the renal pelvis. "We showed that HEY1 was significantly over-expressed in HCC, ICC, and renal cancer while PINK1 was significantly under-expressed in these three cancer types in which HIF was often activated." (PMID 31819034, 2019).
renal clear cell carcinoma (1 paper, 2022). "Moreover, the overexpression of Notch1 intracellular segment in VHL knockout mice revealed accumulation of intracellular fat, cytoplasmic dysplasia nests, and upregulated expression of Hey1 and Hey2 downstream of the Notch pathway, similar to human renal clear cell carcinoma." (PMID 35096263, 2022).
schizophrenia (1 paper, 2024). A major psychotic disorder characterized by abnormalities in the perception or expression of reality. "The network, constructed based on the TFs predicted by genes with higher expression in ECM-altered regions in schizophrenia, is centered around HEY1 and DLX6, both of which are associated with neurogenesis and forebrain and craniofacial development." (PMID 38491019, 2024). "Dopamine dysfunction, long implicated in schizophrenia’s pathophysiology, was further supported by studies showing up-regulation of dopamine transporters with a VNTR domain and altered spontaneous activity upon HEY1 knockout in mice." (PMID 38491019, 2024).
Sepsis (1 paper, 2022). Sepsis is defined as life-threatening organ dysfunction caused by a dysregulated host response to infection. "Sepsis significantly (p < 0.05) attenuated the mRNA expression of Hey1 in mouse aorta as compared to that observed in the mice of SO group (0.38 ± 0.13 vs. 1.13 ± 0.20, n = 7–8)." (PMID 35190630, 2022). "Downstream to the receptor-ligand interaction, mRNA expression of an effector gene (Hey1) was also significantly (p < 0.05) attenuated in septic mouse aorta suggesting an overall decrease in Notch signalling in mouse aorta following polymicrobial sepsis." (PMID 35190630, 2022). "Thus we evaluated the aortic mRNA expression of Hey1 in sepsis." (PMID 35190630, 2022).
soft tissue tumors (1 paper, 2023). "In soft tissue tumors, the shortest paths to HEY1 and FOXO3 had the highest importance." (PMID 37242535, 2023).
triple-negative breast carcinoma (1 paper, 2022). An invasive breast carcinoma which is negative for expression of estrogen receptor (ER), progesterone receptor (PR), and human epidermal growth factor receptor 2 (HER2). "Celastrol can reduce the activation of Notch-1 and the expression of HES-1 and HEY-1 of the downstream target protein and inhibit the stem cells of triple-negative breast cancer, thereby reducing the possibility of distant metastasis." (PMID 36506508, 2022).
uveal melanoma (1 paper, 2022). A melanoma derived from melanocytes of the uveal tract. "JAG2, another NOTCH ligand whose effect may involve HES1 and HEY1, is also critically required for uveal melanoma cell proliferation and motile ability 59,60." (PMID 35673577, 2022). "It is worth noting that primary uveal melanomas also display significant expression of HES1 and HES4 as well as of HEY1-2 and HEYL." (PMID 35673577, 2022).
tumor (81 papers, 2009 to 2025). "Overexpression of HEY1 was significantly associated with more advanced tumor stages and poor overall survival." (PMID 31819034, 2019). "Although earlier studies assumed Notch signaling to be associated with KSHV angiogenesis, its role in tumor growth has now been proven based on the significance of Hey-1 to the development of embryonic vasculatures." (PMID 27447661, 2016). "Expectedly, C8orf4-deficient tumours showed elevated expression levels of NOTCH2 target genes such as HEY1, HES6 and NRARP." (PMID 25985737, 2015). "We also show for the first time that activity of Notch3 in particular, through its target gene, HEY-1, is associated with an aggressive tumour phenotype and an adverse prognosis." (PMID 23226563, 2012). "Consistent with this reduction in NOTCH levels, significant decreases in NOTCH target genes (Deltex1, Hey1, and Hes1) are also observed in tumor-associated T-cells, suggesting that tumor-associated T-cells have repressed NOTCH signaling and potentially decreased effector function." (PMID 30967879, 2018). "In human PC cell lines, the downregulation of PTOV1 induced an upregulation of the endogenous HEY1 and HES1 genes, and reciprocally, the ectopic expression of PTOV1 in PC cells and HaCaT keratinocytes, where Notch acts as tumor suppressor, caused the inhibition of expression of HEY1 and HES1 genes." (PMID 28029646, 2017). "In twin slides, we could also observe that the same Hey1 positive tumor areas concomitantly expressed active Notch3, had increased tumor cell proliferation and presented loss of epithelial markers, suggesting a de-differentiation phenotype." (PMID 26213336, 2015). "In survival analyses, nuclear Notch3 and HEY-1 expression were significantly associated with reduced overall and disease-free survival following tumour resection with curative intent, with nuclear HEY-1 maintaining independent prognostic significance for both outcomes on multivariate analysis." (PMID 23226563, 2012). "Subsequent analyses using subcutaneous tumour and lung metastasis models provided further evidence supporting the involvement of HEY1 in the progression of OS and the occurrence of distant metastasis." (PMID 40531089, 2025). "High expression of Notch receptors (Notch 1 and 4) and components like HES-related protein (Hey1) and Delta-like ligand (DII1) are associated with worse GBM outcomes, such as reduced survival and higher tumor grades 51,52." (PMID 40365286, 2025). "For example, constitutive Notch activation induces the transcriptional repressor Hey1, which suppresses TweakR expression, reducing immune cell recruitment and facilitating tumor escape from immune surveillance." (PMID 41465101, 2025). "HEY1, a transcription factor, has emerged as a significant player in driving tumour progression across diverse cancer types, including OS." (PMID 40531089, 2025). "In the Notch pathway, HEY1 is a crucial downstream target gene that can influence tumor cells' fate through the Notch/HES1/HEY1 pathway." (PMID 37441462, 2023). "Although Notch signalling has been extensively studied in the regulation of embryonic and tumour vascular development, the role of the Notch transcription factors Hey1/Hes1 is not yet fully understood." (PMID 35318338, 2022). "The C-MET/ERK/FRA1/HEY1 axis is mediated by CAF-derived HGF to promote the stemness of tumor-initiating cells." (PMID 36457492, 2022). "The real-time PCR results confirmed that hypoxia significantly upregulated Notch1, Hes1, and Hey1 mRNA expression in tumor cells (P < 0.05)." (PMID 35982489, 2022). "The results from qRT-PCR analysis showed that the expression of Notch2, NICD, Hes1, and Hey1 in murine tumor tissues from NEDD4L-overexpressed group was significantly decreased compared with control group." (PMID 35646490, 2022). "Compared with the tumor volume in the control group, the tumor volume was significantly reduced in the Hey1 interference group but was significantly increased in the Hey1 overexpression group." (PMID 34729100, 2021).
tumor (continued). "Compared with the control group, there were smaller and fewer metastatic tumor islands in the Hey1 interference group and larger and more metastatic tumor islands in the Hey1 overexpression group." (PMID 34729100, 2021). "Treating mice bearing pancreatic cancer xenografts with PF-03084014 (150 mg/kg), alone or combined with gemcitabine, downregulated NICD Hey-1 and Hes-1, resulted in tumor regression, and reduced cancer stem cells." (PMID 33673088, 2021). "The expression of ADAM10, Notch1, Notch2, Notch3, Notch4, Hey1, vimentin and N‐cadherin at the transcript level was significantly upregulated, whereas transcripts of E‐cadherin significantly decreased in tumour tissues versus in normal liver tissues of HCC." (PMID 33955149, 2021). "By contrast, SLIT2, EFNB2, FGF9, and HEY1, which promote tumor angiogenesis, were downregulated in 9F-treated HCT116 cells." (PMID 32106543, 2020). "The appearance of subcutaneous tumors at the experimental endpoint, tumor growth curves, and tumor weight showed that knockdown of HEY1 mRNA inhibited the tumorigenicity significantly." (PMID 32284759, 2020). "Taken together, these results suggest that the knockdown of HEY1 can effectively inhibit 3D tumor cell spheroid formation and stemness in SACC stem cells." (PMID 32025208, 2020). "In line with our expression studies, knockdown of HEY1 repressed tumor growth whereas knockdown of PINK1 augmented tumor growth in vivo." (PMID 31819034, 2019). "HEY1 overexpression was also closely correlated with shorter overall survival and more advanced tumor stages in HCC patients." (PMID 31819034, 2019). "IHC staining also showed that lncAKHE depletion led to reduced expression of HES6 and HEY1 in lncAKHE-silenced tumor tissues." (PMID 29706630, 2018). "To explore the physiological role of HEY1 in HCC, we analyzed the expression levels of HEY1 and found that HEY1 was highly expressed in tumor tissues." (PMID 29212240, 2017). "Summarily, our research demonstrates that LDB2 can inhibit tumor cell proliferation and migration by downregulating HEY1 expression." (PMID 29212240, 2017). "HEY1 was a classic target gene of NOTCH signaling that was shown to promote many kinds of tumor progression." (PMID 29212240, 2017). "We show that bortezomib administration to naïve or tumor-bearing mice upregulates mRNA expression of Hes1 and Hey1 and their protein products." (PMID 26431276, 2015). "Of note, bortezomib reversed tumor-induced downregulation of Notch receptors, Notch1 and Notch2, as well as increased the levels of cleaved Notch intracellular domain (NICD) and downstream targets Hes1 and Hey1 in tumor-draining CD8+T-cells." (PMID 26431276, 2015).
tumor (continued). "Expression of dnMAML1 in Met-1 cells resulted in Hey1 downregulation and poor tumor growth upon subcutaneous injection." (PMID 25592291, 2015). "Endothelial Jagged1 not only up-regulated ECs specific Hey1 transcription and expression but also increased its expression in adjacent tumor cells." (PMID 26213336, 2015). "A significant upregulation of protein levels of Notch1 and Notch2 receptors, and Hes1 and Hey1 products was observed in bortezomib-treated group when compared with tumor alone group." (PMID 26431276, 2015). "Then, E4-ECsScr and E4-ECsJag1KD were co-cultured with MDA-231 cells and the expression of canonical notch downstream target genes Hes1 and Hey1 was determined in tumor cells after sorting." (PMID 25380486, 2014). "The contrasting activities of PTOV1 and HES1 and HEY1 were also tested in HaCaT transformed skin keratinocytes, a cellular model in which Notch has known tumor suppressor functions." (PMID 24684754, 2014). "In summary, this study has identified nuclear expression of Notch3 and HEY-1 in tumours as potentially useful indicators of poor prognosis in PDAC." (PMID 23226563, 2012). "In tissues from inoperable locally advanced and metastatic tumours, nuclear expression of Notch1, -3, -4, HES-1, and HEY-1 (all p≤0.001) was significantly increased compared to expression in resected tumours." (PMID 23226563, 2012). "A role of Notch1 and HEY1 over-expression in embryonal RMS is supported by the inhibition of cell proliferation in tumor cell lines depleted of either Notch1 or HEY1." (PMID 23158439, 2012). "In contrast, HEY-1 was up-regulated in tumours from 33/35 patients (94.2%), with nuclear stain in 11 resected PDAC (26.2%, p = 0.001) and 38 (76%) advanced tumours." (PMID 23226563, 2012). "Other regulated signalling molecules included guanine exchange factors that play a role in an activation of the MAP kinases while several tumor suppressors i.e. Mcc, Hey1, Fat3, Armcx1 and Reck were significantly repressed." (PMID 19812696, 2009). "HEY1 has different functions in normal and tumour tissues, which may be related to its expression level, subcellular localization and interacting proteins." (PMID 40531089, 2025). "Finally, the subcutaneous tumour experiment results also showed that silencing HEY1 inhibits the growth of OS through the CD44/EGFR/FAK pathway." (PMID 40531089, 2025). "HEY1 as a transcriptional suppressor associated with cell division is involved in the epithelial-mesenchymal transition (EMT), which benefits the migration, invasion and anti-apoptosis of tumor cells." (PMID 38227591, 2024). "Moreover, nuclear Notch3 and HEY-1 expression was shown to be significantly associated with reduced OS and DFS following tumor resection." (PMID 39062863, 2024). "While Notch blockade in a tumour’s endothelium results in reduced NO levels, it has been reported that Notch overactivity negatively regulates NO levels in healthy hepatic sinusoidal endothelial cells, possibly due to the control of Hes1 or Hey1." (PMID 35954226, 2022). "Moreover, DNMM1 significantly reduced the number of ALDH1+ and Hey1+ cells in the xenografted tumours." (PMID 35318302, 2022). "Similarly, the Notch target genes Hes1 and Hey1 were found overexpressed in a significant portion of HNSCC tumours, again suggesting hyperactivity of Notch signalling in these tumour tissues." (PMID 34944837, 2021). "Furthermore, the activation of NICD translation into the nucleus regulated the expression of target genes, such as HES1 and HEY1, which play a key role in tumor stemness, metastasis, and multi-drug resistance." (PMID 34001269, 2021). "Notably, the tumor groups showed a low expression level of HEY1 and NR2F1 compared with the normal group." (PMID 34457116, 2021). "Furthermore, endothelial Jagged-1 exerted an angiocrine function by activating Notch 2/HEY-1 in tumour cells promoting proliferation, survival and EMT." (PMID 32575680, 2020).